MX2 (MX dynamin like GTPase 2)
Diseases named in the same sentence as MX2 in open-access papers (continued):
Sharing a sentence is not in itself a finding about the gene and the disease.
infection (continued). "Indeed, we discerned a distinct separation in immune responses between HA-MARV and WT-MARV when MIP-1α, IP-10, and Mx2 were examined on day 3 post-infection." (PMID 27976688, 2016). "Together, these data raised the possibility that the interaction of incoming HIV-1 CA with CPSF6 may help protect infection from MX2-independent IFN-α-induced blocks." (PMID 27279606, 2016). "We next investigated the stage(s) of infection that is blocked in MX2-depleted cells." (PMID 27279606, 2016). "Typhimurium demonstrated a 4-fold induction of the mx2 promoter 74 h after infection." (PMID 23940817, 2013). "Next, we explored whether additional determinants affect the ability of the GTPase-deficient MX2 to restrict infection of primate lentiviruses in the absence of CA-CypA binding." (PMID 38512975, 2024). "Moreover, genetic depletion of Mx2 enhanced oHSV-1 lytic replication in A172 cells, but not in D54 and DU145 cells, suggesting that the association of Mx2 with restricted oHSV-1 infection is cell-specific, not universal." (PMID 34707174, 2021). "We, and others, have previously identified a cell-encoded protein, human myxovirus resistance 2 (MX2), which is expressed upon initiation of an innate immune response and prevents accumulation of HIV-1 DNA within the nucleus, thus imposing a block to infection." (PMID 30496303, 2018). "Due to the observed lack of impact of nucleoporin knockdown on infection of U87-MG cells, we asked whether functional redundancy between nucleoporin-dependent HIV-1 nuclear import pathways in these cells may have occluded the detection of MX2-dependent infection phenotypes." (PMID 30496303, 2018). "The dependence of MX2 activity upon dimerization is reminiscent of fusions between the murine leukemia virus restriction factor Fv1 and cyclophilin A; these chimeric proteins also suppress infection by inhibiting viral cDNA nuclear import, perhaps indicating commonalities in mechanism." (PMID 26446602, 2016). "For example, pDCs in the circulation may have been exposed to free virus particles/proteins either directly by the challenge virus or produced by a limited infection in the mucosal compartment that transiently appeared as free virions in the circulation to selectively activate Mx1 and Mx2." (PMID 24884551, 2014). "Total RNA was extracted 4 and 8 h post-infection, after which the relative levels of IFNβ, OAS1, MX1, and MX2 RNAs were determined by quantitative real-time PCR (qRT-PCR)." (PMID 41585476, 2026). "At h 36, the infection with SIV H1N1 (MOI 0.01) induced increases of approximately 20-, 70-, 30-, and 5-fold in IFN-β, Mx1, Mx2, and IFITM1, respectively, while these changes were 90-, 250-, 300-, and 25-fold for SIV H3N2 (MOI 0.01)." (PMID 40565228, 2025). "Some other infection-responsive genes like IFI144, MX1, MX2, IFIT3, and HLA-DOA were also observed proximal to those altered ERVs, and showed positive co-expressions with their proximal ERVs, wherever they located." (PMID 40176799, 2025). "For this purpose, PBE cells were challenged with SIV H1N1 or H3N2 and the expression of IFN-β and the antiviral factors Mx1, Mx2, IFITM1, OAS1, OAS2, and OASL were evaluated at different hours post-infection." (PMID 40565228, 2025). "Interlinked interactions between the viral capsid (CA), nucleoporins (Nups), and the antiviral protein myxovirus resistance 2 (MX2/MXB) influence human immunodeficiency virus 1 (HIV-1) nuclear entry and the outcome of infection." (PMID 39853118, 2025). "All ISGs were downregulated in all infection groups at 14 dpi, with significant downregulation of MX1 and MX2 in the PJ73 group and JBNU-22-N01 group." (PMID 40459260, 2025). "The induction levels of antiviral genes—including DDX58, OAS1, OAS2, ISG15, MX2, IFI44L, RTP4, and IFNB1—were markedly reduced in KO cells compared to WT cells post-infection." (PMID 40872812, 2025).
infection (continued). "In this study, despite significant production of IFNs in the lung during the infection, ISG15, ISG12(A), MX1, and MX2 genes were downregulated at 14 dpi, suggesting that PRRSV employs strategies to inhibit ISGs and facilitate in vivo replication." (PMID 40459260, 2025). "Our results reveal that infection of CPSF6-NP and MX2 NLS cells resulted in functional nuclear import, as measured by both 2-LTR circles and localization of Gag-Integrase labeled viruses inside the nucleus of these infected cells." (PMID 39823525, 2025). "The 17 DEGs upregulated after infection with huH1N1 were shared with the swH1N1 infection (DDX58 (RIG-I), RSAD2 (Viperin), MX2, MX1, OAS1, ANGPTL4, IRF7, ISG15, IFIT1, ISG12(A), DDX60, BST2, IFI44, XAF1, LGALS3BP, RTP4, and IFI6)." (PMID 39247193, 2024). "Four important antiviral ISGs, MX1, MX2, ISG15, and IFI6, were found to be upregulated after infection with either strains of IAV in the lower trachea." (PMID 39247193, 2024). "CsA addition in HT1080 cells is known to reduce infection of HIV-1WT and abolish the antiviral activity of MX2." (PMID 38512975, 2024). "Our results reveal that infection of CPSF6-NP and MX2 NLS cells resulted in functional nuclear import, as measured by both 2-LTR circles and fluorescently-tagged virus localization." (PMID 38979149, 2024). "Bulk RNA sequencing of suspension organoids at 3, 7, 10, and 14 days post-infection revealed up to 26-fold time dependent promotion of interferon-stimulated genes such as IFIT3, MX1 and MX2, consistent with an innate antiviral response." (PMID 37205380, 2023). "During the infection with CEV genogroup IIa, Mx2 was significantly up-regulated in all strains and peaked on 6 dpi in AS, PS, and Rop." (PMID 37465154, 2023). "Shared genes upregulated with a higher log2 fold change in B/Victoria infection included known anti-viral proteins IFIT1-3, IFITM1, MX2, IFI44L and ISG15 along with mitochondrial-related gene CMPK2." (PMID 37766362, 2023). "In NHBE cells, only MX1, MX2, and OAS1 were significantly over-expressed in SARS-CoV-2-infected cells compared with mock infection (p < 0.05 for MX1 and OAS1; and p < 0.01 for MX2)." (PMID 36298734, 2022). "Further, SARS-CoV-2 infection significantly induced these ISGs in ferret tracheal biopsy samples collected on day 3 after infection compared with mock-treated animals (p < 0.01 for MX1; and p < 0.05 for MX2, ISG15, and OAS1)." (PMID 36298734, 2022). "Clear kinetics of this response were observed during infection with MA08, starting with the production of ISGs, IFIT2 and MX2 at 48 hpi." (PMID 34671358, 2021). "Therefore, we hypothesized that Mx2 inhibits the delivery of incoming viral DNA to the nucleus for repressing oHSV-1 T1012G productive infection in resistant cell line A712 and that knockdown of Mx2 would enhance nuclear translocation of viral genome in A172 cells." (PMID 34707174, 2021). "ISGs and immune response genes such as IFIT1, IFIT2, IFIH1, MX1, MX2, and RSAD2 were highly down-regulated in response to all viruses at later time points of infection, confirming our transcriptome data." (PMID 33791243, 2021). "Infection with either of the four strains resulted in an up-regulation of IL-6, IL-10, IFN-λ, IFN-γ, IP-10, MX-2, and TNF-α expression in the range of 10- to 1000-fold compared to non-infected hamsters." (PMID 34049240, 2021). "For the interferon regulated genes, Ct infection induced a significant increase in the MX1 and MX2 mRNA fold change (between ~2 and 3.5) at 12, 24 and 36 hpi, while CMPk2 mRNA fold change increased between 36 and 48 hpi to ~2.6 and 2, respectively." (PMID 34684219, 2021). "We observed that in vitro infection with GCRV induced the expression of IFN1, Mx2, IL-1β, and TNFα, indicating the initiation of antiviral response." (PMID 34068469, 2021).
infection (continued). "The results showed that the expression of antiviral genes (e.g., PKR, OAS1, and Mx2) and inflammatory cytokines (e.g., IFN-α and TNF-α) were significantly reduced within 0–4 h post-infection (P < 0.05)." (PMID 32133381, 2020). "MRNA expression levels of ISGs, such as myxovirus-resistant 2 (Mx2) and GCRV induced gene 1 (gig1), in cells overexpressing VP4 were reduced compared to the levels in control cells upon GCRV infection or when uninfected." (PMID 32268551, 2020). "In the present study, we found that the expression of antiviral genes (e.g., PKR, OAS1, and Mx2) and inflammatory cytokines (e.g., IFN-α and TNF-α) were significantly reduced within 0–4 h post-infection." (PMID 32133381, 2020). "We found that the mRNA expression levels of ZAP, MX2, MX1, PKR, OASL, and ISG15 were significantly higher in the Lp-1s treated group than in the TGEV infected group at various points after infection." (PMID 31781061, 2019). "When alone, MX2 and MX2 (GMX1) sustained the same viral replication kinetics, at least during the first 3 days of infection, followed by a slightly lower viral production for MX2, consistent with previous results." (PMID 31722207, 2019). "In the case of HIV-1G89V, whose infection was inhibited by NUP88 and NUP214 depletion in HeLa cells, expression of MX2 completely restored infection." (PMID 30084827, 2018). "We further found that, like the type I interferon-induced cellular anti-viral proteins SAMHD1 and MX2, SFN treatment blocks infection after entry, but before formation of 2-LTR circles." (PMID 27093399, 2016). "The capsid binding proteins MX2 and, conditionally, CPSF6, both appear to block infection prior to entry in the nucleus." (PMID 26181333, 2015). "Increased RNA expression levels of the ISGs Mx2, Rsad2, and USP-18 mRNA were found in both WT and IRF-1−/− 2 days post infection, followed by a decline." (PMID 24675692, 2014). "Importantly, infection with LSDVΔ122 partially but significantly enhanced IFN-β-induced transcription of antiviral ISGs, including ISG56, MX2, and RSAD2, compared to wild-type LSDV." (PMID 41525414, 2026). "We found that, in addition to a broad induction of ISGs (for example, DTX3L, OAS3, RTP4, IRF7, MX2, IFIT3, IFIH1), only IFNB1 and, more robustly, IFNL1-like and IFNL3-like were induced in virus-infected organoids at 1 and 3 days after infection compared to the uninfected controls." (PMID 40399606, 2025). "We observed a modest though significant reduction in HIV-1WT infection (~2.3-fold) as well as a reduction in MX2 sensitivity in RANBP2∆Cyp cells, suggesting that in addition to CypA, CA-RANBP2-Cyp interactions affect MX2 activity against HIV-1." (PMID 39853118, 2025). "In agreement with IFN-I resistance of cell-to-cell infection of macrophages, IFNα-induction of APOBEC3G and 3A, Mx2, and likely other IFN-induced factors such as the Vpu-counteracted Bst-2/tetherin protein, does not affect macrophage infection by cell-cell fusion." (PMID 40294108, 2025). "CPSF6-NP NLS and MX2 NLS constructs in T cells and macrophages behaved largely similarly as they did in HeLa cells, with the exception that the CPSF6-NP NLS chimera supported comparatively less infection of THP-1 cells." (PMID 38979149, 2024). "Several ISGs, including MX1, MX2, and OAS1, were upregulated in 170-infected animals at many different time points but were generally only significantly upregulated in CL8 animals at weeks 1 and 2 post-infection." (PMID 38317183, 2024). "Therefore, we further confirmed the antiviral response of Mx2 during CEV genogroup I and IIa infections." (PMID 37465154, 2023). "Results showed that MX1, MX2 and OAS1 were over-expressed in SARS-CoV-2-infected A549 cells (p < 0.01 for MX1, ISG15, and OAS1; and p < 0.05 for MX2), and Calu-3 cells (p < 0.05 for MX1, ISG15, and OAS1; and p < 0.01 for MX2) compared with mock infection." (PMID 36298734, 2022).
infection (continued). "Decreases in CNS antiviral genes could certainly result in the development of a more robust infection in this compartment, and a recent study noted an inverse correlation in expression of MX1, OAS1, and MX2 expression with SIV RNA levels in the CNS." (PMID 35494221, 2022). "At the transcriptome level, the high expression levels of viral sensors MDA5 (IFIH1), R1G-1 (DDX58), and ISGS (ISG15, Mx1, Mx2, RSAD2, IFIT3, and IFIT5) and transcription factors like IRF-7 and STAT-1 that induce ISG expression were found in lymphocytes during virulent PPRV infection." (PMID 34631844, 2021). "These ISGs, which include MX1, MX2 and BST2, were found to be upregulated in hPIV1-infected cells by at least 7-fold compared to hPIV3 infected cells at both early and late time points after infection." (PMID 34529742, 2021). "We found multiple instances in which MX2 acted to increase, rather than inhibit infection of an HIV-1 CA mutant, in a manner which indicates that the outcome of the interaction between MX2 and the viral CA is dependent upon Nups and CypA." (PMID 30084827, 2018). "MX1 can inhibit a number of viruses, but not retroviruses, while MX2 was recently shown to inhibit infection by HIV-1 and other primate lentiviruses." (PMID 30084827, 2018). "In a third cell line (HOS), MX2 was not well expressed using the inducible vector and therefore only effects of cell-cycle and CypA:CA interaction on infection were measured therein." (PMID 30084827, 2018). "In addition, six genes (SLFN12, MX2, TRIM30A, GBP1, GBP6, and IFIH1) were common to 15 dpi and the early infection period." (PMID 29147886, 2018). "FIV infectivity and MX2 resistance were also unaffected by most Nup depletions in HT1080 cells, but a small number of knockdowns (NUP93, NUP205, NUP160) were significantly deleterious to FIV infection in HOS cells." (PMID 30084827, 2018). "Modest enhancement of infection by MX2 was also observed for the HIV-1G89V whose capsid does not bind CypA, in both HeLa and HT1080 cells, and irrespective of cell-division." (PMID 30084827, 2018). "These cells could produce higher amounts of other antiviral proteins in response to virus such as those observed in this study: MX2, TRIM22, APOBEC3G, and of immunoregulators such as ERAP2, further preventing productive infection." (PMID 28243241, 2017). "Inhibition of HIV-1WT infection by chimeric MX1 expressing the N-terminal 91 amino acids of MX2 (MX1MX2-NTD) was reversed by CsA treatment in both HeLa and HT1080 cells (even enhancing HIV-1WT infection in CsA-treated HT1080 cells to a greater degree than MX2)." (PMID 38512975, 2024). "Treatment of MDBK and bovine white blood cells with IFN-α, as well as infection with bovine herpes virus 1, and bovine rotavirus upregulated Mx1 gene expression whereas, infection of bovine endometrial cells with ncp BVDV (Pe515nc strain) reduced/inhibited Mx1 and Mx2 gene expression." (PMID 39224597, 2024). "Furthermore, other types of IFN that induce Mx2 expression, such as various IFN-α subtypes and IFN-λ, act cumulatively or might be preferentially induced early after infection." (PMID 36558888, 2022). "However, transfection of siRNA against MX2 did not restore HAdV-C5 reporter gene expression, suggesting that the effects of MxB on HAdV-C5 infection were indirect or unspecific." (PMID 29773792, 2018). "However, CsA treatment abolished the MX2 sensitivity of HIV-1N74D, and even caused MX2 to modestly increase HIV-1N74D infection, particularly in non-dividing HT1080 cells." (PMID 30084827, 2018). "Interestingly, mx2 induction was not significantly different after infection with low (MOI 10-20) and high (MOI 100-200) amounts of both bacteria." (PMID 23940817, 2013).
infection (continued). "Our findings reported here would indicate that HIV-1 CA interacts with MX2 regardless of its conformation/interaction with other cellular cofactors, whether this interaction results in abortive infection or altered integration targeting is determined (at least in part) by CA-Cyp interactions." (PMID 39853118, 2025). "Interestingly, while deletion of RANBP2-Cyp had marginal effects on infection by HIV-1G89V CA as expected, the ability of MX2 to enhance infection of this mutant was reduced in RANBP2∆Cyp cells, suggesting there may also be CA-independent effects of the Cyp domain on MX2 activity." (PMID 39853118, 2025). "However, this infection could not be rescued by MX2-specific siRNAs, suggesting MxB-independent effects or indirect effects of MxB on HAdV-C5 infection." (PMID 29773792, 2018). "While these pro-inflammatory cytokines were not increased, Ct infection of pOECs did lead to a significant increase in the mRNA expression of the interferon regulated genes MX1, MX2, and CMPK2." (PMID 34684219, 2021). "Corresponding infections with CPXV and LV induced IFN-β but not Mx2, while TBEV induced both IFN-β and Mx2." (PMID 22194969, 2011). "Interestingly, the expression of MX2, IFIT2, OASL and OAS2 was up-regulated after infection with HEV-3f in both pig livers and HepaRG cells but not in pig livers infected with HEV-3c." (PMID 38058490, 2023). "Therefore, we investigated expression of IL-15 and ISGs, such as APOBEC3G, ISG15, ISG20, MX1, MX2, and RSAD2, after infection with R5-tropic, non-opsonized (HIV) and complement-opsonized (HIV-C) HIV-1 strains (BaL and YU-2)." (PMID 34634939, 2021). "Indeed, under these MX2 knockdown conditions, MX2 antiviral activity was abolished, and doxycycline addition alone did not rescue HIV-1N57S infection." (PMID 30084827, 2018). "However, the majority of antiviral ISGs, including OAS1, MX2, IFI6, IFITM1, IFI27, and IFTM2, were downregulated in cells transduced with MyD88 (in the presence or absence of infection) and were also downregulated in cells infected with UL88-deficient HCMV vs wild-type HCMV." (PMID 40638072, 2025). "We expressed a panel of (C-terminally myc tagged) MX2 mutants that altered the N-terminal CA-interacting domain, GTP binding and hydrolysis, or oligomerization in HeLa and HT1080 cells and first determined their effect on HIV-1WT infection in the presence and absence of CsA." (PMID 38512975, 2024). "Finally, similar to MX2T151A, MX2T151D inhibited HIV-1WT infection in the presence of CsA as well as infection of HIV-1G89V CA, demonstrating that phosphorylation at residue T151 does not determine CA-CypA-dependent antiviral activity of MX2 since MX2T151A and MX2T151D exhibited a similar phenotype." (PMID 38512975, 2024). "Instead, as suggested by the similar levels of Mx2 mRNA between non-infected and PUUV-Suo infected cells, the interferon-mediated immune system of Mygla.REC.B cells does not efficiently sense PUUV-Suo infection, which could facilitate a persistent PUUV-Suo infection in these cells." (PMID 32316667, 2020).